TBK1 (TANK binding kinase 1)
Diseases named in the same sentence as TBK1 in open-access papers (continued):
Sharing a sentence is not in itself a finding about the gene and the disease.
viral infection (continued). "Together, we conclude that virus infection triggers TBK1-mediated ZNF268a phosphorylation, which subsequently leads to ZNF268a stabilization and recruitment of SETD4 to TBK1, followed by TBK1 mono-methylation, thereby potentiating TBK1 for antiviral immune signaling." (PMID 37926288, 2023). "However, as for TBK1 ubiquitination, C. albicans significantly promoted viral infection-induced TBK1 ubiquitination." (PMID 37243289, 2023). "Thus, our findings uncover a mechanism by which the PTK2B oligomerization induced by viral infection plays a positive role in regulating antiviral signaling by promoting TBK1 phosphorylation and oligomerization." (PMID 37989995, 2023). "During a viral infection, TBK1, IKK, and IRF3 form a complex." (PMID 37376653, 2023). "TBK1 could recruit to STING or MAVS during viral infection, which localized closely to the endoplasmic reticulum." (PMID 37854611, 2023). "Our results showed that IRF3/5/7 are expressed in cytoplasm, generally in an inactive state like their mammalian counterparts, and after stimulation by poly(I:C) and TBK1 transfection or virus infection, they rapidly undergo the cytoplasmic to nuclear translocation." (PMID 35464458, 2022). "Given that GSNOR inhibits s-nitrosation of TBK1 to enhance innate immunity, it is still unclear whether viral infections can hijack GSNOR to antagonize antiviral immunity." (PMID 36189363, 2022). "Viral infection induces the E3 ligase AMFR/gp78 to constitutively interact with STING and mediate the K27-linked ubiquitination of STING, which is critical for the STING-mediated recruitment of TBK1 and IRF3 following DNA virus infection." (PMID 35992663, 2022). "Optimized TBK1 action was indispensable for virus clearance, and overexcited TBK1 activation might accelerate inflammatory damage during viral infection." (PMID 35646147, 2022). "The ubiquitin–proteasome pathway plays an important role in protein degradation, and ubiquitination of TBK1 is an important method of modulate the production of type I interferons during virus infection, during which process, viral proteins and host proteins participate." (PMID 36329446, 2022). "To investigate whether TBK1 modulation influences viral infection, we utilized mouse embryonic fibroblasts (MEFs) from wildtype (TBK1+/+), heterozygous TBK1 knockout (TBK1+/-), and homozygous TBK1 knockout (TBK1-/-) mice." (PMID 36044516, 2022). "It was first identified that NEDD4 directly targets TBK1 to induce K27-linked polyubiquitylation at K344 for degradation via the ALP, leading to the downregulation of type I IFN signaling in the late stages of virus infection." (PMID 36498930, 2022). "However, the acetylation of TBK1 at Lys241 during the early stage of viral infection enhanced the recruitment of IRF3 to TBK1." (PMID 32772249, 2021). "Furthermore, viral infection triggers various molecular pathways downstream of these PRRs, which converge to recruit Tank-binding Kinase 1 (TBK1) and homologue IκB kinase epsilon (IKKε), to activate interferon regulatory factor 3 (IRF3)." (PMID 33419081, 2021). "We found that viral infection induced TBK1 S-nitrosation at Cys423." (PMID 34678655, 2021). "This interaction is enhanced upon viral infection and dissociates TBK1 from the protein complex." (PMID 33525590, 2021). "Additionally, the TRAF3 substrate TBK1 was also recruited to TFG upon viral infection or stimulation with Poly(I:C)." (PMID 33411856, 2021). "To investigate potential mechanisms by which this enhancement of vomocytosis may be accomplished, we tested a TBK1:IKKε inhibitor in the presence of a viral infection." (PMID 32106253, 2020). "It is well known that TBK1 and IKKɛ regulate the production of type 1 IFNs during viral infection." (PMID 32967676, 2020). "We found that endogenous β-arrestin 2 could be associated with TBK1 and TRAF3 during virus infection." (PMID 33243993, 2020).
viral infection (continued). "Therefore, blocking TBK1 activity should prevent the induction of interferons, reduce host response, and facilitate viral infection." (PMID 32967676, 2020). "GSK-3β binds to TBK1 and induces TBK1 phosphorylation upon viral infection." (PMID 32849638, 2020). "Furthermore, we demonstrated that activation of RNA innate immune sensing by overexpression of TBK1 in S10-3-EZ cells decreased viral infection." (PMID 33424806, 2020). "β-arrestin 2 did not associate with TBK1 or TRAF3 without virus infection, while the situation changed after infection." (PMID 33243993, 2020). "A serine-rich cluster is present in the duck sequence near Serine 496 and contains the motif HLGLS, which resembles the consensus pLxIS motif containing (human) Serine 442 that becomes phosphorylated by IKKβ and TBK1 upon viral infection, leading to recruitment and phosphorylation of IRF3." (PMID 32272772, 2020). "Our data indicate that HDAC6 could inhibit TBK1 activity during dsRNA viral infection to suppress type 1 interferon (IFN) responses." (PMID 32849638, 2020). "Once STING is activated by viral infection, mitochondrial DNA or endoplasmic reticulum stress, it could recruit TANK-binding kinase 1 (TAK1) and IRF3, and then phosphorylate IRF3 by TAK1." (PMID 31121492, 2019). "THOC7 interacted with TBK1 and was increased after viral infection." (PMID 30769920, 2019). "TBK1 functions as an important player in inflammatory responses, autophagy and mitophagy, the insulin signaling pathway and innate immunity against bacterial and viral infections." (PMID 29441066, 2018). "As TBK1 isoforms lacked a partial KD, we theorized that TBK1_tv1 and TBK1_tv2 might inhibit TBK1-mediated activation under viral infection." (PMID 29441066, 2018). "In the context of a virus infection, endogenous TBK1 was also coimmunoprecipitated with HRTV NSs." (PMID 28680969, 2017). "A report has demonstrated that a viral infection-induced E3 ligase AMFR/gp78 interacts with STING constitutively and mediates K27-linked ubiquitination of STING, which is critical for STING-mediated recruitment of TBK1 and IRF3 after DNA virus infection." (PMID 28534493, 2017). "IRF3 is phosphorylated and activated by active TBK-1/IKKε upon viral infection." (PMID 28589097, 2017). "Treatment of LPS could suppress the levels by subverting the polyI:C- and viral infection-mediated TBK1, IRF3, and NF-κB response." (PMID 27826297, 2016). "Thus, degradation of MAVS by NSP1 not only affects its interaction with downstream molecules (TBK1) but also inhibit downstream aggregate formation on mitochondrial membrane in response to virus infection." (PMID 24643253, 2014). "Therefore, RNF11 is likely recruited to both TBK1 and IKKi only when they are activated in response to virus infection." (PMID 23308279, 2013). "Further analysis of the effect of C6 on these protein complexes may shed some light on the mechanism by which TBK1 and IKKε are activated - and inhibited - during viral infection." (PMID 21931555, 2011). "However, as IKKɛ expression in most cell types requires virus-induction, IKKɛ likely plays a redundant role to TBK1 during the late stages of virus infection." (PMID 21994600, 2010). "In addition, the related pathways of virus infection disease, such as kaposi sarcoma-associated herpesvirus infection, human papillomavirus infection, and Epstein–Barr virus infection, were enriched, with FAS and TBK1 being identified as pivotal genes." (PMID 40423420, 2025). "Unlike the four previously reported patients with AR TBK1 deficiency and systemic autoinflammation, including early-onset arthritis and vasculitis, the patient with AR TBK1 deficiency described here had recurrent confirmed or suspected viral infections and no autoinflammation." (PMID 41608123, 2025). "In addition, the p-TBK1 level was increased in Rnf144b KO cells following viral infection." (PMID 39285245, 2024).
viral infection (continued). "Our main goals in this study were to develop the bestpossible predictive models for TBK1 inhibitors that could be usedby research scientists in their quest to discover effective drugsagainst wide range of diseases such as cancer, viral infections, andinflammatory disorders." (PMID 39289178, 2024). "However, when viral infection occurs, TBK1 interacts with cytosolic ZNF268a and directly phosphorylates Serine 178 of ZNF268a, which could promote the protein stability of ZNF268a and significantly increase the expression level of ZNF268a in the cytoplasm." (PMID 37926288, 2023). "Therefore, enhancing the expression of TBK1-related activators and targeting related repressors may be the key to the future treatment of viral infections." (PMID 36189363, 2022). "We determined that decreased phosphorylation of IRF7 and TBK-1 in CD14dimCD16+ monocytes, cDC1, and cDC2 and a subsequent decrease in STING activation in older adults was associated with the impaired primary IFN induction during the early phase of simulated viral infection." (PMID 35849213, 2022). "Moreover, consistent with previous reports showing the recruitment of TRAF3 to MAVS as an important process leading to downstream signaling, the silencing of TFG also blunted the activating transautophosphorylation of TBK1 on Ser172 (p-TBK1 Ser172) normally observed upon viral infection." (PMID 33411856, 2021). "These DUBs mainly regulate the polyubiquitination levels of RIG-I, STING, MAVS, TRAFs, and TBK1, which function at different levels of this pathway, and this finding implies the physiological importance of these master proteins in innate immunity during viral infections." (PMID 34707613, 2021). "Finally, in addition to direct regulation of immune cells, GCN5 and PCAF suppress TANK-binding kinase 1 (TBK1) activity in the cytoplasm by blocking phosphorylation events on TBK1, ultimately inhibiting innate immune signaling and interferon production upon viral infection." (PMID 34112237, 2021). "In addition, different TRAFs may form hetero-oligomers to activate TBK1 and IKKε differentially, in this way further fine-tuning virus infection triggered innate immune responses." (PMID 29125880, 2017). "Under viral infection conditions, MAVS is known to promote polymerization through CARD-CARD interactions, which recruit IRF3 by IKK-ε and TBK1, leading to the activation of IFN-β." (PMID 40944942, 2025). "The role of acetylation in viral infections is emerging as many host proteins are acetylated during infection including RIG-I, TANK-binding kinase 1 (TBK1), cGMP-AMP synthase (cGAS; a sensor of cytosolic DNA)." (PMID 40519923, 2025). "Following virus infection, we observed the restoration of IRF3 phosphorylation and IFNB mRNA expression in cells complemented with TBK1, with further enhancement upon Frk overexpression." (PMID 40012791, 2025). "In the context of viral infections, AhR signaling was shown to downmodulate IFN-I responses via the induction of TIPARP, which inhibits TANK-binding kinase 1 (TBK1) downstream of RIG-I activation, or by inhibiting NF-κB signaling." (PMID 41321306, 2025). "In human THP-1 cells, ferrous iron potently attenuated the viral infection-induced expression of IFN-β and the activation of IRF3, TBK1, and STAT1, resulting in the enhancement of viral replication." (PMID 40595467, 2025). "GSDMD‐CT negatively regulates IFN‐I signaling during viral infection by triggering autophagic degradation of RIG‐I and TBK1." (PMID 40539222, 2025). "SIRT7 decreases IRF3/IRF7 phosphorylation to block the interaction between tbk1 and IRF3/IRF7, resulting in the suppression of antiviral responses, disruption of SIRT7 increases the survival rate of carp during virus infection." (PMID 40636259, 2025). "The TBK1/IKKε complex is a key adapter in antiviral innate immune signaling, with both proteins phosphorylating IRF3 to promote IFN-I production and combat viral infections." (PMID 40548751, 2025).
viral infection (continued). "TBK1 is the crucial kinase in innate immune system, it stimulates transcription factor IRF3 and NF-κB in multiple signaling pathways during viruses infection to induce interferon and inflammatory factor expressions." (PMID 38449860, 2024). "Upon virus infection, IRF3, as a critical transcription factor in the IFN induction pathway, can be phosphorylated and activated by TBK1, and then phosphorylated IRF3 translocates from the cytoplasm into the nucleus, eliciting the expression of antiviral IFNs." (PMID 38285487, 2024). "Upon virus infection, AXIN1 undergoes a phase separation triggered by phosphorylated TANK-binding kinase 1 (TBK1)." (PMID 39384753, 2024). "In the case of viral infection, Lgals3bp forms complex with Traf6 or Traf3, and subsequently recruits TAK1 and TBK1, which then signal the translocation of the transcription factors NF-κB, IRF3, and IRF7 from the cytoplasm to the nucleus." (PMID 38279161, 2024). "In their experiments, Crlf3 interacted with TANK-binding kinase 1 (TBK1) and promoted its degradation via ubiquitination, presumably preventing cell response to viral infection." (PMID 38448973, 2024). "After viral infection, these receptors recruit downstream molecules, including MAVS, TBK1, or RIP2 to activate IRF3, a common molecule in all innate immune signaling pathways." (PMID 38516932, 2024). "The STING C-terminal tail recruits TBK1 and IRF3 to potentiate expression of IFN-I during virus infection." (PMID 37902401, 2023). "During viral infection, IRF3 and NF-κB can be phosphorylated by the protein kinase TBK1 and subsequently translocated to the nucleus as activated transcription factors." (PMID 37222520, 2023). "There were some reports that the inhibition of the interaction of HSP90A with TBK1, IRF3, and Cdc37 impairs the innate immune response to viral infection." (PMID 37442062, 2023). "A previous study has shown that MAPK signaling increases the phosphorylation of TBK1 and IRF3 upon viral infection." (PMID 37833891, 2023). "During viral infection, the adaptor proteins MAVS and STING are phosphorylated by the kinase IKK/TBK1 in response to stimulation, inducing type I interferons (IFNs) and other antiviral molecules." (PMID 37143582, 2023). "During viral infection, histone deacetylase 9 (HDAC9) deacetylates tank-bound kinase 1 (TBK1) to activate TBK1 phosphorylation, leading to an increase in type I IFN." (PMID 37396372, 2023). "During viral infection, AHR-induced PARP7 can interact with TBK1 and catalyze its mono-ADP-ribosylation, which suppresses the activation of TBK1 and subsequent phosphorylation of IRF3." (PMID 36839575, 2023). "After viral infection, STAT6 is aggregated in the endoplasmic reticulum and phosphorylated by TBK1, which then dimerizes into the nucleus and regulates the expression of antiviral immunity genes." (PMID 37143582, 2023). "We further demonstrated that Bmp4 promotes the phosphorylation of Tbk1 and Irf3 through the p38 MAPK pathway, thereby inducing the production of type I IFNs in response to virus infection." (PMID 37833891, 2023). "As per viral infection, NIC and virus treated cells (at 48 h) also saw an up-regulation of GABARAPL1, MAP1LC3A, USP30, BMF, and TBK1; WDR81 was also down-regulated in the NIC and virus treatment at 48 h." (PMID 37901834, 2023). "We next examined key molecules in the RIG‐I pathway and found that TBK1 and IRF3 phosphorylation was severely compromised in response to viral infection despite restoration of MAVS level following protease inhibitors treatment." (PMID 36216581, 2022). "Several TRIMs were also recruited to negatively regulate the activation or stability of TBK1 and IRF3/7 during virus infection." (PMID 36498930, 2022). "During viral infection, TRIM23 mediates TBK1-dimerization and activation, which is required for early autophagic induction and p62 phosphorylation for viral clearance." (PMID 35395857, 2022).
viral infection (continued). "TRIM18 was shown to recruit protein phosphatase 1A (PPM1A) to dephosphorylate TBK1, which inactivates TBK1 and blocks its interactions with upstream adaptors MAVS and STING, thereby dampening type I IFN mediated antiviral signaling during viral infections." (PMID 35909127, 2022). "Taken together, the results of TBK1 overexpression, TBK1 knockdown, in vitro and in vivo experiments support the role of TBK1 in IFN-β induction in ducks following viral infection." (PMID 35632751, 2022). "Collectively, these data suggest that TRIM18 recruits PPM1A to dephosphorylate TBK1 for its inactivation and blocks interaction of TBK1 with its upstream adaptors MAVS and STING for signal transduction during virus infection." (PMID 35909127, 2022). "RNA (SeV and VSV) or DNA (HSV) virus infections upregulate Siglec1 expression in macrophages and indirectly recruit TRIM27 to mediate the Ub-dependent degradation of TBK1." (PMID 36498930, 2022). "DTX4 is recruited by NLR Family Pyrin Domain Containing 4 (NLRP4) to mediate the proteasomal degradation of the Serine/threonine-protein kinase (TBK1), thereby restricting the induction of type 1 IFN following viral infection." (PMID 35204725, 2022). "TBK1 undergoes autophosphorylation and ubiquitination to facilitate the activation of downstream adaptors (e.g., IRF3 or NF-κB) during viral infections." (PMID 35412346, 2022). "Mechanistically, RKIP binds to and facilitates TBK1 auto-phosphorylation after viral infection, and significantly, RKIP itself is a substrate of TBK1." (PMID 35892864, 2022). "Second, TRIM18 interacts with TBK1 and blocks its interactions with upstream adaptors MAVS and STING for preventing signal transduction during virus infection." (PMID 35909127, 2022). "Upon viral infection, STING also acts as a scaffold protein for TANK-binding kinase 1 (TBK1) and IRF3 and links them to the MAVS complex in mitochondria." (PMID 36569852, 2022). "Following TBK1 silencing, we infected cells at MOI 0.01 over a time course of 0, 6, and 24 h to observe the dynamics of viral infection over time." (PMID 36044516, 2022). "In similar lines, our study shows that TBK1 is yet another host PK that is cleaved by HIV-1 PR to inhibit type 1 IFN production possibly to dampen innate immunity and promote viral infection." (PMID 33986734, 2021). "TBK1 plays an important role in antiviral innate immunity as it mediates the activation of IRF 3 to induce IFN-α/β following viral infection." (PMID 34679772, 2021). "At an early time of viral infection, MAVS activates the cytosolic TANK-binding kinase 1 (TBK1) and IκB kinase-ε (IKKε)." (PMID 34305530, 2021). "DTX4 recruitment to TBK1 was shown to be dependent on the NOD protein family member NLRP4, which interacted specifically with activated (phosphorylated) TBK1 upon viral infection." (PMID 33808506, 2021). "This phosphatase antagonizes TANK-binding kinase (TBK1)-mediated phosphorylation and aggregation of STING, which is orchestrating innate immune responses upon detection of cytosolic DNA as a sign of viral infection or mitochondrial damage." (PMID 33882943, 2021). "Moreover, recent studies suggest that recruitment of TBK1 to STING may perform a more significant role in antagonist virus infection and restrict oncogenesis, which expands the horizon of cGAS-STING axis function besides IRF3 and nuclear factor-κB (NF-κB) signaling." (PMID 34966372, 2021). "Previous studies determined that, during viral infection, USP38 inhibits type I interferon pathway by degrading TBK1, thereby inhibiting the synthesis of type I IFN." (PMID 34696459, 2021). "We show here that during the early stage of viral infection, the acetylation of TBK1 was increased, and the acetylation of TBK1 at Lys241 enhanced the recruitment of IRF3 to TBK1." (PMID 32772249, 2021).